FGF23 (fibroblast growth factor 23)
Diseases named in the same sentence as FGF23 in open-access papers (continued):
Sharing a sentence is not in itself a finding about the gene and the disease.
hypophosphatemia (continued). "If the i:cFGF23 ratio is unavailable, in the context of hypophosphatemia, an elevated intact FGF23 level may be used to infer an FGF23-mediated hypophosphatemic process, given its reflection on the biological activity of FGF23, such as in our case." (PMID 41445556, 2025). "His course was notable for hypophosphatemia refractory to phosphate supplementation, accompanied by hypocalcemia, secondary hyperparathyroidism, suppressed 1,25-dihydroxy vitamin D, and markedly elevated fibroblast growth factor 23 (FGF23)." (PMID 41362568, 2025). "The concentration of PTH, especially FGF23, is usually decreased secondary to hypophosphatemia." (PMID 41008628, 2025). "Similarly to MAS, CSHS is characterized by the overproduction of FGF23, secreted by osteocytes in affected dysplastic bones, resulting in hypophosphatemia, bone pain, rickets, long bone deformity, impaired growth and mobility." (PMID 40491596, 2025). "Importantly, available evidence suggests that the majority of GACI survivors develop FGF23-mediated hypophosphatemia in childhood, thus making GACI and ARHR2 a phenotypic continuum or single spectrum of disease." (PMID 40176950, 2025). "However, the increased vulnerability to hypophosphatemia and higher skeletal-related morbidity in patients FD with compared to other FGF23 excess disorders supports a more robust therapeutic target." (PMID 41480037, 2025). "It was assumed that FGF23 levels in Hyp mice are below the threshold required for left ventricular hypertrophy development or that hypophosphatemia may prevent the deleterious effects of FGF23 on the heart." (PMID 40152980, 2025). "It was suggested that TIO might modify the clinical progression of psoriasis by secreting elevated levels of FGF23, leading to the worsening of psoriasis and hypophosphatemia." (PMID 40291321, 2025). "Since elevated FGF-23 underlies the disorder, phosphate supplementation is not expected to sustainably correct hypophosphatemia, thus the most common treatment recommendation was to discontinue or, if not possible, switch iron preparations." (PMID 41146174, 2025). "Elevated intact FGF23 concentrations in children with hypophosphatemia might seem to indicate FGF23-dependent renal phosphate wasting, e.g., autosomal dominant hypophosphatemic rickets, X-linked hypophosphatemia, or tumor-induced osteomalacia." (PMID 41008628, 2025). "Denosumab is an emerging therapy that may help reduce FD lesion pain and reduce lesion growth, while burosumab is being investigated for its potential role in improving pain related to FGF23-mediated hypophosphatemia and osteomalacia." (PMID 40538772, 2025). "All these processes lead to hypophosphatemia when FGF23 is in excess." (PMID 39888445, 2025). "As RAS activation is known to induce FGF23 and thus hypophosphatemia through diminishing phosphate reabsorption and increasing urinary phosphate excretion, treatment with the MEK inhibitor trametinib was started at a dosage of 0.025 mg/kg/day (0,25mg) in a hospital setting at the age of 26 months." (PMID 40611284, 2025). "Moreover, 1,25(OH)2D is valuable parameter in distinguishing FGF23-mediated and non-FGF23-mediated hypophosphatemia." (PMID 40502410, 2025). "Some single case reports describe FGF23 levels and hypophosphatemia in patients affected by NF1, hypothesizing a possible paraneoplastic production of FGF23 by subcutaneous or plexiform neurofibromas." (PMID 40133996, 2025). "In a recent study evaluating a cohort of pediatric and adult patients with different causes of renal hypophosphatemia, a cut-off point for intact FGF23 of 27 pg/mL was 100% sensitive and specific in distinguishing FGF23-dependent from FGF23-independent hypophosphatemia." (PMID 41008628, 2025). "Moreover, the inappropriately low 1,25-dihydroxy vitamin D in the setting of significant hypophosphatemia is reflective of the inhibitory effect of FGF23 on the proximal tubular expression of 1-alpha-hydroxylase enzyme." (PMID 40922882, 2025).
hypophosphatemia (continued). "We hypothesized that hypocalcemia is an under-recognized complication of i.v. iron infusion that, similar to hypophosphatemia, develops in the setting of excess FGF23." (PMID 41445551, 2025). "In addition to osteochondrodysplasia, we noted dramatic increases in plasma FGF23 and hypophosphatemia, driven by upregulated Fgf23 expression and protein levels in bone, with consequent undermineralization." (PMID 41473314, 2025). "Evaluation of the etiology of hypophosphatemia requires an algorithmic approach to determine whether hypophosphatemia is renally-mediated, FGF23-mediated, acquired or inherited." (PMID 41445556, 2025). "Despite hypophosphatemia, a high FGF23 level of 133 kRU/l persisted (normal value: 26–110)." (PMID 41008628, 2025). "In addition to the FGF23-dependent forms of hypophosphatemia, there are other FGF23-independent forms, for example those linked to malabsorption or primary tubular hyporeabsorption of phosphate." (PMID 39377903, 2025). "This case highlights the importance of measuring FGF23 levels in cases of FS of unknown origin with marked hypophosphatemia." (PMID 39888445, 2025). "In conclusion, evaluating the etiology of hypophosphatemia requires an algorithmic approach to determine whether it is renally mediated, FGF23-mediated, acquired, or inherited." (PMID 41445556, 2025). "Another form of exogenous substance-induced FGF23-related hypophosphatemia is intravenous iron preparation-induced FGF23-related hypophosphatemia, which may have a common pathophysiologic background with alcoholic osteomalacia." (PMID 39963340, 2025). "According to a systemic review of 769 articles, hypophosphatemia (99.8%), increased FGF23 (95.5%), increased ALP (94.9%), and decreased 1,25(OH)2D (69.8) were observed at TIO diagnosis, and serum Pi and FGF23 levels were normalized in approximately 91.5% and 81.4% of patients, respectively." (PMID 41227266, 2025). "Those with a family history of hypophosphatemic osteomalacia and those with no identified acquired causes of FGF23-mediated hypophosphatemia should be referred for comprehensive genetic testing." (PMID 41445556, 2025). "The upregulation of serum FGF23 results in hyperphosphaturia, hypophosphatemia, and decreased levels of calcitriol due to the inhibitory effect on renal 25-hydroxyvitamin D3 1-α-hydroxylase with the resultant hypo-mineralization of calcified tissues, such as bone and teeth." (PMID 38818505, 2024). "Our data confirmed the hypophosphatemia and high FGF23 levels in hyp mice." (PMID 39666728, 2024). "Based on two clinical observations of profound hypophosphatemia in the setting of acute hepatitis, our study investigates the hypothesis of acute FGF23 liver expression." (PMID 39525686, 2024). "Potential adverse effects of conventional treatment include nephrocalcinosis, hypercalcemia, hypercalciuria, hyperparathyroidism, and gastrointestinal issues, as well as exacerbated hypophosphatemia through elevation of circulating FGF23 levels and parathyroid hormone." (PMID 39539413, 2024). "The index clinical case involves acute alcoholic hepatitis complicated by profound hypophosphatemia due to phosphate diabetes, revealing a major production of both FGF23 C-terminal fraction (cFGF23) and bio-intact form (iFGF23, 39 751 RU/mL, N: 21–91; and 228.6 pg/mL, N: 22.7–93.1, respectively)." (PMID 39525686, 2024). "Fibroblast growth factor 23 (FGF23) could trigger thissequence, but—as in this case—patients may still suffer from hypophosphatemia long after FGF23has recovered." (PMID 38746050, 2024). "Moreover, the level of 1,25-OH2-vitamin D was inappropriately low in the context of hypophosphatemia, and both intact and C-terminal FGF23 levels were elevated." (PMID 38806758, 2024).
hypophosphatemia (continued). "In an intervention study in healthy adult females, the administration of ammonium chloride for 7 days, resulting in chronic metabolic acidosis, led to an elevated fractional phosphate excretion, consequent hypophosphatemia, and hence a reduction in FGF23 plasma levels." (PMID 39537770, 2024). "XLH is an inherited disease of phosphate metabolism in which inactivating mutations of the Phosphate-Regulating Endopeptidase Homolog, X-Linked (PHEX) gene lead to local and systemic effects including hypophosphatemia, bone defects such as rickets and osteomalacia, and elevated levels of FGF23." (PMID 39666728, 2024). "Consistent with our prior studies, and despite the “rescue diet,” Cyp27b1 null females had hypocalcemia, hypophosphatemia, secondary hyperparathyroidism, lower FGF23, very low calcitriol (99.6 ± 14.1 pmol/L, above the 20 pmol/L detection limit due to fetal-placental sources), and higher 25(OH)D3." (PMID 38477809, 2024). "As these data only raise a hypothesis, dedicated experimental studies are needed to confirm the link between acute hepatitis, hepatic overproduction of FGF23 and renal-wasting hypophosphatemia." (PMID 39525686, 2024). "However, a strength of our study is the comparison of the two mouse models both of which exhibit hypophosphatemia–either acquired induced by diet, or genetically-induced—but opposite levels of FGF23." (PMID 39666728, 2024). "However, hyp mice, the murine model of XLH, exhibit hypophosphatemia and high serum FGF23 levels, along with low number of circulating RBCs, hemoglobin, and hematocrit compared to wild-type mice." (PMID 39666728, 2024). "Finally, the initial very high FGF23 levels were observed during hypophosphatemia, making it unlikely that the increase was a reaction to phosphate supplementation." (PMID 39525686, 2024). "In summary, we demonstrated that Bbx deficiency in the whole body, as well as specifically in osteoblasts/osteocytes, increases FGF23 expression, resulting in hypophosphatemia and subsequent bone abnormalities, including mechanical weakness, shortness, and a low BMD and BV." (PMID 39482539, 2024). "In conclusion, loss of Cyp24a1 in fetal mice causes hypercalcemia, modest hypophosphatemia, and increased FGF23, but no alteration in skeletal development." (PMID 38577520, 2024). "We found that HRAS hyperactivity in bone, not skin, caused excess of bioactive intact FGF23, hypophosphatemia, and osteomalacia." (PMID 36943390, 2023). "This might be a group of patients where FGF23 could be of additional value to measure when hypophosphatemia occurs." (PMID 35665817, 2023). "PHEX regulates FGF23 expression whereas high FGF23 concentration in serum results in hypophosphatemia and low concentration of 1,25-dihydroxyvitamin D by damaging renal reabsorption of phosphate and 1a-hydroxylase activity, as well as increasing the activity of renal 24-hydroxylase." (PMID 37818127, 2023). "In our study, the very mild increase in Fgf23 levels and the lack of hypophosphatemia suggests that the phenotypic differences in response to glomerular injury is indeed caused by soluble Klotho, and not by elevated Fgf23 and/or lower phosphate." (PMID 36813870, 2023). "For example, patients with chronic FGF23-non-related hypophosphatemia (e.g., Fanconi syndrome, vitamin D deficiency) do not develop ectopic ossifications." (PMID 37530996, 2023). "Simultaneously, FGF-23 suppresses the activity of renal 1α-hydroxylase and promotes the activity of 24-hydroxylase, leading to insufficient active vitamin D and reduced intestinal phosphate absorption, further exacerbating hypophosphatemia." (PMID 37768354, 2023). "While the clinical spectrum of CSHS varies greatly from individual to individual in terms of the extent and location of bone and skin lesions and the degree of FGF23-mediated hypophosphatemia, in the majority of patients, the most debilitating manifestation is hypophosphatemia." (PMID 36943390, 2023).
hypophosphatemia (continued). "We hypothesized that reduction of osteocyte-produced FGF23 in Dmp1-null mice might lead to correction of hypophosphatemia and improve bone growth and mineralization, similar to Hyp mice." (PMID 37943605, 2023). "Once FGF23 excess is established and/or genetic causes and other causes of hypophosphatemia have been ruled out in children, young adults, or those with suggestive family history, imaging to locate the causative tumor is performed." (PMID 36511653, 2023). "Animal models of hypophosphatemia indicate that the excess of FGF23 exerts a marked adverse effect on growth plate structure and dynamics and that blocking FGF23 action reverses this action and stimulates longitudinal growth as well as formation and mineralization of bone." (PMID 37047636, 2023). "While the role of DMP1 as a pro-mineralization factor is well documented, its direct contribution in the pathogenesis of impaired mineralization in ARHR is less clear, as most effects are attributed to failure of DMP1 to suppress FGF23 and FGF23-induced hypophosphatemia." (PMID 37943605, 2023). "Both direct and indirect actions of FGF23 contribute to hypophosphatemia." (PMID 37048797, 2023). "While we have not measured intestinal Pi absorption in this model, it is possible that the residual increase in 1,25(OH)2D contributes to increased intestinal Pi absorption, which in turns contributes to the full correction of the hypophosphatemia despite residual increases in FGF23 and PTH." (PMID 37943605, 2023). "Reduction of FGF23 levels fully corrects hypophosphatemia in Dmp1KO mice." (PMID 37943605, 2023). "Another recent study shows similar results in adults, with an intact FGF23 cut point of 27 pg/mL distinguishing FGF23-mediated from FGF23-independent hypophosphatemia, and a cFGF23 cut point of 90 RU/mL identifying specifically TIO from FGF23-independent hypophosphatemia." (PMID 37047636, 2023). "In addition to wasting urinary Pi with resultant hypophosphatemia, these animals are known to have reduced FGF23 levels." (PMID 36821389, 2023). "Consistent with this hypothesis, a previous study in the Hyp mouse model of XLH used a Col2.3-cre to delete Fgf23 in osteoblasts and achieved a similar correction of hypophosphatemia but complete corrections of FGF23 levels, bone growth, and bone morphology." (PMID 37943605, 2023). "Because PHEX, DMP1, and ENPP1 all induce FGF23-related hypophosphatemia, they may affect common pathophysiological mechanisms inducing enthesopathies and spinal ligament ossifications." (PMID 37530996, 2023). "Additional solutes (potassium, bicarbonate and/or calcium) may be required in non-FGF23 related hypophosphatemia if there is proximal renal tubular acidosis with aminoaciduria." (PMID 37074534, 2023). "Therefore, the higher serum FGF23 level, the more severe hypophosphatemia is, and the weaker mechanical load at the lower extremities in the TIR/O patients possibly caused their extremely poorer skeletal status than the XLH patients." (PMID 35769089, 2022). "In autosomal recessive hypophosphatemic rickets type 2 (ARHR2), ectonucleotide pyrophosphatase/phosphodiesterase family member 1 (ENPP1) fails to keep FGF23 levels low due to inactivating mutations in the ENPP1 gene resulting in hypophosphatemia." (PMID 35084563, 2022). "However, in a few cases FGF23 was within the normal range, which is still abnormal in the setting of hypophosphatemia." (PMID 35857061, 2022). "This phenotype could be mimicked in an animal model by using an adenovector-induced increased expression of α-klotho, leading to high levels of circulating α-klotho, accompanied by a very steep rise of FGF23 and hypophosphatemia." (PMID 35629904, 2022). "Burosumab-twza was developed for the treatment of FGF-23 related hypophosphatemia; however, for the purpose of this review, its indication for the treatment of X-linked hypophosphatemia (XLH) in pediatric patients (but including adult treatment) will be discussed." (PMID 36304528, 2022).
hypophosphatemia (continued). "In tumor-induced osteomalacia, tumor cells — often but not exclusively benign mesenchymal tumors — secrete FGF23, resulting in hypophosphatemia as a hallmark." (PMID 35084563, 2022). "Subsequent hypophosphatemia induces a decrease in systemic FGF-23 levels." (PMID 35414099, 2022). "Because CKD prevents hypophosphatemia, the increase in FGF‐23 associated with iron infusion is not followed by hypophosphatemia and osteomalacia associated with hypophosphatemia after repeated iron infusion is not observed." (PMID 35426179, 2022). "The typical biochemical features of these patients are hypophosphatemia, due to renal phosphate wasting, and low or inappropriately normal 1,25 dihydroxy-vitamin D (1,25(OH)2D3), due to excessive secretion of tumor-derived FGF-23." (PMID 35381903, 2022). "Preoperative FGF-23 is a predictor of persistent post-transplant hypophosphatemia." (PMID 35602513, 2022). "The lack of genetic mutation and skeletal abnormalities in these patients denotes that FGF23 may contribute to the clinical features either directly or via hypophosphatemia." (PMID 36553684, 2022). "In addition, FGF23 also impairs the production of 1,25(OH)2D through inhibition of 1α-hydroxlase and stimulation of 24-hydroxylase, which further exacerbates hypophosphatemia." (PMID 35769089, 2022). "Due to the phosphaturic effects of PTH, this mechanism may prolong hypophosphatemia after FGF23 returns to normal levels." (PMID 35790696, 2022). "Although there was a lack of research on tumor-promoting effects of high expression of FGF-23, the important role of FGF/FGFR signaling in prostate cancer and paraneoplastic diseases mediated by FGF23 overexpression, such as hypophosphatemia, also suggested a link between FGF-23 and tumors." (PMID 35663394, 2022). "Active, intact FGF23, a key component in phosphate regulation, increases after treatment with certain IV iron preparations, leading to increased urinary excretion of phosphate and, thus, hypophosphatemia." (PMID 35790696, 2022). "Furthermore, the osteocyte-specific deletion of Fgfr1 partially restored the overproduction of FGF23 and ameliorated hypophosphatemia and rickets in Hyp mice." (PMID 36246908, 2022). "- FGF-23 levels decreased by 97% at 4 weeks after transplant but were still above normal. - FGF-23 levels, but not PTH levels, were independently associated with post-transplant hypophosphatemia." (PMID 35602513, 2022). "RNS patients who survive infancy may manifest hypophosphatemia related to FGF23 excess and dental abnormalities." (PMID 36246908, 2022). "In mice, diet-induced iron deficiency during pregnancy and nursing resulted in elevated serum concentrations of total-FGF23 and intact-FGF23 (as measured using an assay which only detects the intact hormone), hypophosphatemia, and reduced serum concentrations of 1,25(OH)2D in their pups." (PMID 33675347, 2021). "Even under these conditions, furin deficient mice did not develop hypophosphatemia and in fact displayed higher serum phosphate level despite a near complete impairment of FGF23 cleavage." (PMID 34149625, 2021). "Second, some specific iron preparations, such as ferric carboxymaltose, are proposed to enhance the initiation of O-glycosylation irrelevant to the actual serum phosphate level, resulting in inappropriately high intact FGF23 levels with concomitant hypophosphatemia." (PMID 34901334, 2021). "We hypothesized that a certain change derived from the hospitalized environment, such as alcohol abstinence, led to the improved FGF23-related hypophosphatemia." (PMID 34901334, 2021). "Although very rare, increased FGF23 production may be associated with mesenchymal tumors or Linear Nevus Sebaceous Syndrome (LNSS), leading to hypophosphatemia and rickets." (PMID 34199067, 2021).